EGFR (epidermal growth factor receptor)
Diseases named in the same sentence as EGFR in open-access papers (continued):
Sharing a sentence is not in itself a finding about the gene and the disease.
cervical carcinoma (314 papers, 2005 to 2026). A carcinoma arising from either the exocervical squamous epithelium or the endocervical glandular epithelium. "Four genes associated with survival of cervical cancer patients were selected by survival by univariate analysis: EGFR, TNF-α, VEGFA and MDM2 (P<0.1)." (PMID 40238841, 2025). "Overexpression of EGFR has been associated with cervical cancer development, invasion, and metastasis." (PMID 37894282, 2023). "Overexpression or activation of EGFR has been linked to the development of several malignancies, including lung, head and neck, and cervical cancer." (PMID 37310466, 2023). "In this sense, the presence of EGFR has also been linked with primary and metastatic cervical cancer." (PMID 36231664, 2022). "It was estimated that 90% of cervical cancers overexpress EGFR, and high expression of EGFR is associated with poorer prognosis." (PMID 35070983, 2021). "They include EGFR inhibitors 47–49 and PARP-1 inhibitors 50,51, because of the expression of EGFR 18 and presence of homologous recombination-related gene mutations 52 in cervical cancer." (PMID 33570867, 2021). "The JNK pathway contributes to HPV-associated cervical cancer cell proliferation, anchorage-independent growth, migration, invasion and EMT Inhibiting the JNK pathway reduced EGFR’s expression levels in HPV-associated cervical cancer cell lines." (PMID 34439095, 2021). "EGFR mutations are significantly correlated with a highly differentiated grade in patients with cervical cancer." (PMID 33802174, 2021). "It has been known that cervical cancer with EGFR overexpression is associated with poor therapeutic efficacy and prognosis." (PMID 32850421, 2020). "Supportive of this association, we showed that paclitaxel-resistant CSCs were highly enriched in both EGFR-mutated paclitaxel-resistant HeLa229 and SiHa cervical cancer cells." (PMID 31772161, 2019). "Mining TCGA database uncovered that high expression of EGFR was significantly associated with poor disease-free survival in cervical cancer patients with chemotherapy." (PMID 31772161, 2019). "Consistent with published work, we found that increased MUC1 expression in cervical cancer cells was associated with increased phosphorylation and total level of EGFR." (PMID 28796259, 2017). "Overexpression of EGFR has been associated with poor prognosis in cervical cancer, making EGFR an obvious candidate for therapeutic targeting." (PMID 27783105, 2017). "Correctly evaluating the association between EGFR expression and survival in cervical cancer patients is essential to understanding the mechanisms of action underlying anti-EGFR therapies." (PMID 27438047, 2016). "This meta-analysis demonstrates that EGFR overexpression is closely associated with reduced survival in patients with cervical cancer." (PMID 27438047, 2016). "Our combined analysis of 23 published studies that included 2,505 patients with cervical cancer yielded summary statistics demonstrating that in cervical cancer patients, high EGFR levels are associated with lower OS and DFS." (PMID 27438047, 2016). "In this study, we perform a meta-analysis of the association between EGFR expression and survival in cervical cancer patients." (PMID 27438047, 2016). "The overexpression of EGFR is thought to be negatively associated with survival in cervical cancer patients, and the relationship between EGFR overexpression and altered survival in patients with cervical cancer has therefore been studied for many years." (PMID 27438047, 2016). "In this report, we show that stress conditions, including protein synthesis inhibition, UV irradiation, and hyperosmosis, cause endocytosis and degradation of EGFR in cervical cancer HeLa cells." (PMID 27034618, 2016). "Of relevance to our findings are previous reports showing that EGFR is overexpressed in cervical cancer and is associated with poor prognosis and decreased survival of cervical cancer patients." (PMID 26417066, 2015).
cervical carcinoma (continued). "Here we demonstrate that PTEN destabilization is induced by EGFR- or oncogenic PI3K mutation-mediated AKT activation in cervical cancer." (PMID 26183061, 2015). "Causes of EGFR upregulated expression include receptor overexpression and activating mutations; however, in cervical cancer EGFR mutations are undetectable or uncommon." (PMID 26209091, 2015). "EGFR is expressed at moderate to high levels in cervical cancer, and its expression is associated with clinical stage and poor prognosis." (PMID 23936413, 2013). "The cervical cancer results for the top ranked candidate compounds revealed a strong association with the EGFR pathway." (PMID 21305029, 2011). "Previous studies have shown EGFR to be frequently overexpressed in primary cervical cancer; however, the mechanism of EGFR activation (i.e., gene amplification or activating mutation) in cervical cancer is poorly understood." (PMID 21730982, 2011). "In a systematic review, the EGFR signaling is associated with poor prognosis and response to therapy in cervical cancer patients primarily treated with chemoradiation." (PMID 21896192, 2011). "The EGFR expression, amplification, and mutation in cervical carcinomas were assessed by immunohistochemistry, fluorescence in situ hybridisation, and PCR–SSCP, respectively, and correlated with clinical data collected by a retrospective chart review." (PMID 21730982, 2011). "Thus, the AFAP1-AS1/miR-7-5p/EGFR axis was closely associated with the progression and gemcitabine tolerance of cervical cancer cells, providing potential targets for the treatment of cervical cancer." (PMID 39574469, 2024). "High expression of EGFR is associated with poor outcomes in cervical cancer." (PMID 37372319, 2023). "EGFR mutations are rare in high-grade cervical lesions and invasive cervical cancer." (PMID 38414930, 2023). "In cervical cancer, the overexpression of EGFR has been associated with a poorer prognosis." (PMID 37310466, 2023). "The increased growth rate of cervical cancer cell lines may be caused by the decreased stability of EGFR at the post-transcriptional level due to changes in functional levels of HPV E6/E7 proteins." (PMID 38414930, 2023). "The epidermal growth factor receptor (EGFR) has been associated with cervical cancer progression." (PMID 33886813, 2021). "High EGFR expression is associated with poor prognosis in cervical cancer." (PMID 33668730, 2021). "Others up regulated circRNAs in cervical cancer cells are circATP8A2 promoting cervical cancer progression through the circATP8A2/miR-433/EGFR axis, and circ_0067934 which binds miR-545 and is associated with advanced cancer stage, lymph node metastasis, and poor prognosis." (PMID 32154165, 2020). "However, the elevated expression of EGFR was significantly associated with poor disease-free survival in chemo-treated cervical cancer patients." (PMID 31772161, 2019). "Data from our working group show that EGFR and HER2 are also present in cervical cancer lines and that they could be involved in the pathogenesis and progression of cervical lesions, due to a direct association of EGFR expression and HPV infection." (PMID 31198791, 2019). "Given that the TCGA analyses showed that EGFR status was associated with disease-free survival in cervical cancer patients with chemotherapy, we sought to test whether erlotinib could be a useful agent to target CSCs." (PMID 31772161, 2019). "EGFR is commonly expressed in normal cells of the basal layer of epithelium but overexpression in tumor cells is closely associated with reduced survival in patients with cervical cancer." (PMID 29160417, 2017). "It is therefore reasonable to assume that there is a relationship between EGFR gene mutations and EGFR expression and that EGFR gene mutations may also be useful for predicting responses to EGFR inhibitors in patients with cervical cancer." (PMID 27438047, 2016).
cervical carcinoma (continued). "EGF/EGFR signaling events are associated with accelerated tumor progression of cervical cancer." (PMID 23936413, 2013). "Mutations in EGFR have been shown to be rare in high-grade invasive cervical cancer." (PMID 23936413, 2013). "Our results, however, demonstrate that EGFR mutation is unlikely in cervical cancer." (PMID 21730982, 2011). "Overexpression of the EGFR is associated with a poorer prognosis in patients with cervical cancer." (PMID 16721365, 2006). "Also, EGF receptor (EGFR) is frequently found to be upregulated in cervical cancer and the EGFR amplification is associated with poor prognosis and shorter patient survival, thereby establishing the biological relevance for exploring the significance of EGF in cervical CSCs." (PMID 29777148, 2018). "However, because of EGFR mutations are very rare in cervical cancer and data limitations, we were unable to analyze these hypotheses." (PMID 27438047, 2016). "In summary, our results indicate that the EZH2–PTEN–AKT axis is a key driver of reduced EGFR-TKI sensitivity in radiation-adapted cervical cancer cells." (PMID 41156200, 2025). "HPV E6/E7 have been shown to enhance YAP/TAZ activity through interactions with upstream Hippo regulators and EGFR-related pathways, contributing to cervical cancer progression." (PMID 41470136, 2025). "Our study identifies a mechanistic link between radiation-acquired adaptation and reduced sensitivity to EGFR-targeted therapy in cervical cancer." (PMID 41156200, 2025). "Most cervical cancers are also induced by virus and express EGFR, just like nasopharyngeal carcinoma." (PMID 40335598, 2025). "EGFR overexpression in cervical cancer ranges from 9–90% depending on the disease stage and the study methodology." (PMID 40991529, 2025). "There is evidence that EGFR is overexpressed in 70–90% of cervical cancer, and thus can be considered an effective target for patients with cervical cancer." (PMID 40335598, 2025). "Blocking EGFR activity with AG1478 or EGFR knockdown in cervical cancer cells resulted in the elimination of YAP-induced cell proliferation." (PMID 39936032, 2025). "In cervical cancer, inhibition of EGFR phosphorylation leads to downregulation of the stemness marker SOX2 and a reduction in the CSC population in CaSki and HeLa cell lines." (PMID 41373619, 2025). "To visualize receptor‐mediated internalization of Cy5‐K‐EGFRR in cells, we performed uptake experiments using wild‐type and EGFR‐knocked‐down cervical carcinoma HeLa Kyoto cells." (PMID 40104837, 2025). "Another theory is that the HPV E5 protein induces an increase in Epidermal Growth Factor Receptor (EGFR) activation in cervical cancer." (PMID 41516122, 2025). "Knockdown of EGFR can inhibit the proliferation, migration and invasion, and promote apoptosis of cervical cancer cells." (PMID 40309242, 2025). "Elevated EGFR expression correlates with cervical cancer progression, from LSIL to HSIL and cervical carcinoma." (PMID 40002177, 2025). "Propofol can suppress cervical cancer cell viability, and enhance cisplatin-mediated apoptosis by inhibiting the EGFR/JAK2/STAT3 pathway, thereby enhancing the anti-tumor effect of cisplatin." (PMID 40309242, 2025). "In general, the AFAP1-AS1/miR-7-5p/EGFR axis was tightly related to the progression and gemcitabine tolerance of cervical cancer, providing potential targets for the management of cervical cancer." (PMID 39574469, 2024). "Nonetheless, further evaluation would be important because the E5 oncoprotein can enhance EGFR signaling through direct and indirect mechanisms in cervical cancer." (PMID 39599846, 2024). "Previous research shows that the occurrence and development of cancers including cervical cancer are affected by abnormal expression of EGFR." (PMID 39574469, 2024). "Taken together, AFAP1-AS1 exerts oncogenic characteristics and promotes gemcitabine resistance of cervical cancer cells via the miR-7-5p/EGFR axis." (PMID 39574469, 2024).
cervical carcinoma (continued). "In particular, cervical cancer (CC) emerged as a tumor type exhibiting a robust inverse association between RKIP and EGFR expression, a finding that was further validated in a cohort of 202 patient samples." (PMID 38927888, 2024). "Our cellular experiments showed that naringenin can inhibit the proliferation, migration, and invasion of cervical cancer cells, and further western blot confirmed that naringenin achieves these effects by EGFR/PI3K/AKT/mTOR pathway." (PMID 38253629, 2024). "Cynaroside and Astragalin exert their cervical cancer inhibitory functions by regulating several signaling proteins (e.g., EGFR, STAT3, CCND1, IGFIR, ESR1)." (PMID 38003540, 2023). "Large prospective multi-institutional studies should be considered to further explore the relationship between EGFR and survival in cervical cancer patients." (PMID 38414930, 2023). "It is well known that cervical cancer develops and spreads as a result of the EGFR/AKT/mTORC1 signaling pathway and its connection to HPV infection." (PMID 37947608, 2023). "EGFR is expressed in many normal tissues as well as many solid tumours like cervical cancer, lung adenocarcinomas, epithelial tumours of the head and neck and glioblastomas." (PMID 38414930, 2023). "Our data indicated that ABHD11-AS1 promoted cervical cancer progression by activating EGFR signaling, preventing FUS-mediated degradation of ABHD11 mRNA." (PMID 38146687, 2023). "To explore the potential relationship between EGFR signaling activity and cisplatin responsiveness in cervical cancer patients, we analyzed the transcriptome of The Cancer Genome Atlas (TCGA) cervical cancer patients." (PMID 37165076, 2023). "The strengths of this study lie in the fact that it is the first of its kind in Nigerian cervical cancer patients and it has contributed to the knowledge of EGFR and HER2 expression as well as their relationship to survival in cervical cancer patients." (PMID 38414930, 2023). "The interaction of cervical cancer’s EGFR/AKT/mTORC1 signaling pathway with HPV infection leading to cervical cancers forms a strong plinth to determine the role of C1orf74 in oncogenesis and further progression of the disease." (PMID 37947608, 2023). "Several studies have shown that EGFR was overexpressed in 6%–100% of cervical cancer tissue samples." (PMID 38414930, 2023). "In line with the available literature, a relevant subgroup of cervical cancers appears to harbor EGFR/PTEN/mTOR-pathway alterations, which, as we demonstrated, correlate with ER expression." (PMID 37623437, 2023). "In cervical cancer, E5 induces the more efficient entry of epidermal growth factor receptor (EGFR) into cell surfaces, accelerating the signaling of growth factors." (PMID 37876923, 2023). "In regard to EGFR/PTEN/mTOR-pathway alterations, the literature consistently reports mTOR to be active in cervical cancer and to be a key pathway modulating HPV-associated cell signaling alterations." (PMID 37623437, 2023). "Taken together, our data demonstrate that the hyperactivation of EGFR signaling pathway contributes to the cisplatin resistance in cervical cancer cells." (PMID 37165076, 2023). "The present study is also the first to describe potential associations between EGFR/PTEN/mTOR-pathway alterations and ER expression levels in cervical cancer." (PMID 37623437, 2023). "We found that the expression levels of Arl4A and EGFR in two tested epithelial cervical carcinoma cell lines, HeLa and C33-A, were significantly different." (PMID 38030597, 2023). "MiR-665 has been shown to inhibit cervical cancer malignant progress by targeting two cell surface receptors, EGFR and TGFBR1." (PMID 37894282, 2023). "In cervical cancer development, HPV infection is associated with cytoplasmic EGFR which is involved in cervical cancer aetiology." (PMID 38414930, 2023).
cervical carcinoma (continued). "EGFR overexpression has been identified in various types of cervical cancer, and preclinical studies have shown that inhibition of EGFR signalling can lead to decreased cell proliferation, migration, and invasion in cervical cancer cell lines." (PMID 37310466, 2023). "Increasing the protein level of EGFR promotes the growth and drug resistance of cervical cancer cells." (PMID 37894282, 2023). "Previous study reported that a single dose of radiation induced EGFR expression in cervical cancer tissue, suggesting the role of EGFR in RT resistance." (PMID 35565268, 2022). "HPV E5 protein can up-regulate the expression of COX-2 and MMP-7, and it has been proved that E5 protein can promote the invasion and spread of cervical cancer by activating the NF-κB and EGFR pathways." (PMID 35645817, 2022). "HPV oncoproteins, E5 and E6, have been shown to regulate the activation and augmentation of epidermal growth factor receptor (EGFR), which is associated with poor prognosis in cervical cancer." (PMID 35620479, 2022). "In cervical cancer cells, propofol is able to induce cisplatin-mediated cellular apoptosis through repression of the EGFR/JAK2/STAT3 pathway." (PMID 35517791, 2022). "To ensure that the antiproliferative effect of JWG-071 in endometrial and cervical cancer cells expressing EGFR was due to inhibition of ERK5, we analyzed the effect of MEK5 deletion by generating stable CRISPR/Cas9 MEK5 knockout Ishikawa and HeLa cell lines." (PMID 36123565, 2022). "CD109 is drastically expressed in cervical cancer and upregulates epidermal growth factor receptor (EGFR)-mediated STAT3 phosphorylation, enabling cervical cancer cell migration and proliferation, and supporting cancer cell phenotype." (PMID 35508982, 2022). "Because the EGFR gene is overexpressed in 80% of cervical cancer tumors, an anti-viral targeting E6/E7/E5 oncoproteins or related signaling pathways, such as an anti-EGFR agent, can play a critical role in preventing cancer progression." (PMID 36276117, 2022). "For example, Hippo pathway activation was found to encourage proliferation and migration of cervical cancer cells through a positive signaling loop involving the epidermal growth factor receptor (EGFR)." (PMID 35094292, 2022). "For cervical cancer, a French group reported that the combination of EGFR/HER3 dual antibody and chemoradiotherapy enhanced cancer cell death in cervical squamous cell carcinoma cells in vitro and a mouse model experiment." (PMID 35565268, 2022). "In cervical cancer cells, RTKs, including EGFR and PDGFRα, were significantly downregulated and Akt-mTOR activation was largely inhibited after TN treatment." (PMID 39282148, 2022). "Level of p-ERK1/2 has been linked with activation of HPV E6/E7 in cervical cancer cells, we then determined transcription of HPV E6 and E7 in the controls and EGFR-overexpressing HNSCC cell lines by qRT-PCR." (PMID 36333293, 2022). "It remains unanswered, however, if EGFR signaling is related somehow to components of the fibrinolytic system in cervical cancer." (PMID 33886813, 2021). "Quercetin exerted a synergistic effect on cisplatin-treated cervical cancer cells primarily through downregulating the protein levels of EGFR, MYC, CCND1, and ERBB2 and upregulating CASP8." (PMID 35070983, 2021). "Nearly two decades ago, two independent reports documented nuclear EGFR status in bladder and cervical cancers using IHC." (PMID 34295309, 2021). "In cervical cancer, propofol heightens the cisplatin-triggered cancer cell apoptosis via blocking EGFR/JAK2/STAT3 axis." (PMID 34775376, 2021). "Hippo/YAP signaling pathway plays a critical role in the progression of cervical cancer and can further interact with the ErbB2 and EGFR RTKs to form a positive feedback autocrine/paracrine loop." (PMID 34745942, 2021).